SPRY1 (sprouty RTK signaling antagonist 1)
Diseases named in the same sentence as SPRY1 in open-access papers (continued):
Sharing a sentence is not in itself a finding about the gene and the disease.
sarcopenia (1 paper, 2017). Progressive decline in muscle mass due to aging which results in decreased functional capacity of muscles. "Regardless, in addition to maintaining skeletal muscle regenerative potential, Spry1 manipulation provides a viable approach for counteracting sarcopenia-related NMJ deterioration and aged muscle function decline." (PMID 28583253, 2017). "Although it is unclear which resident cell(s) within COPD or aged biopsies possessed the heightened ERK activity, it would be of interest to determine sarcopenia outcomes upon myofiber-specific Spry1 overexpression." (PMID 28583253, 2017).
thyroid carcinoma (1 paper, 2024). "First, expression of Spry1 in the thyroid carcinoma cell line TT induced a proliferative arrest with traits of cellular senescence both in vitro and in xenografts." (PMID 38670941, 2024). "First, overexpression of Spry1 in a thyroid cancer cell line reduces its proliferation in vitro and in xenografts, concomitant with an increase of p16ink4a and SA-β -Gal." (PMID 38670941, 2024).
Ureteral obstruction (1 paper, 2023). Obstruction of the flow of urine through the ureter. "In addition, miR-21-5p promotes inflammation by activating the SPRY1/ERK/NF-kB signal pathways in unilateral ureteral obstruction mice." (PMID 37228607, 2023).
viral infection (1 paper, 2020). "Therefore, the downregulation of SPRY1 may be a positive response against the viral infection." (PMID 32859030, 2020).
tumor (49 papers, 2010 to 2026). "The four different SPRY isoforms (SPRY1-4) are implicated in different types of cancer, acting as oncogenes or tumor suppressors depending on the SPRY isoform and the malignancy." (PMID 41516252, 2025). "Bioinformatics analyses were also employed to investigate the association of SPRY1 expression with patient survival, tumor grade, and subtypes publicly available datasets." (PMID 35910677, 2022). "Together, these results indicate that suppression of Spry1 reduces MDA-MB-231 TNBC tumor growth and metastasis, and this effect is associated with an increased epithelial phenotype." (PMID 26976794, 2016). "This study also showed that SPRY1 expression was closely associated with tumor angiogenesis." (PMID 35910677, 2022). "SPRY1 and SPRY2 were shown to be downregulated in a variety of cancers, including liver, prostate, and lung tumors, implying a unique tumor-suppressive function.﻿ Conversely, SPRY1′s high expression in tumors harboring Ras/Raf mutations to tumor progression suggests its role in cancer malignancy." (PMID 35910677, 2022). "Interestingly, results from a study on glioblastoma multiforme have suggested that Spry1 expression might be closely associated with tumor angiogenesis." (PMID 39953610, 2025). "Downregulation of PTEN reduces apoptosis and enhances angiogenesis through the HIF-1α signaling pathway, while suppression of PDCD4 and SPRY1 further facilitates tumor cell proliferation, migration, and invasion." (PMID 41511367, 2026). "Along this line, we have recently reported that Spry1 expression was significantly elevated in metastatic cutaneous melanoma (CM) respect to the primary tumor." (PMID 39953610, 2025). "In the last years, it has become increasingly clear that Spry1 can display tumor promoting or suppressive functions depending on the cancer type and/or microenvironmental features." (PMID 39953610, 2025). "In contrast, the reduced protein expression of SPRY1 in NPC tumors corresponded to the EBV-positive cells in the tumor epithelial compartment." (PMID 35394843, 2022). "Acting as a downstream target of fibroblast growth factor receptor (FGFR), SPRY1 inhibits MAPK by inhibiting the phosphorylation of ERK to prevent tumor growth." (PMID 35740349, 2022). "In EwS patients, SPRY1 expression positively correlates with improved survival, suggesting a tumor suppression role in EwS." (PMID 35740349, 2022). "We investigated how the expression levels of CRNDE, FREM2, and SPRY1 genes were connected with the “old” and “new” tumor types." (PMID 36613601, 2022). "Lack of Sprouty 1 and 2 enhances survival of effector CD8+ T cells, and mice with a T cell-selective deletion of Spry1 show enhanced responses to a tumor vaccine." (PMID 32471032, 2020). "Mice in which Spry1 is selectively deleted in T-cells demonstrate enhanced responses to tumor vaccines and subsequently more robust tumor rejection compared to control mice." (PMID 32731503, 2020). "In agreement with this notion, Spry1-/- T cells were shown to have more potent cytolytic activity against lymphoma and melanoma tumor cells." (PMID 32731503, 2020). "Spry1 function in cancer has proven elusive, and it is likely dependent on tumor type, and genetic context." (PMID 32444628, 2020). "In our study, the expressions of SPRY1‐4 in 20 pairs of fresh tumour tissues were detected with qPCR, and in 108 cases of paraffin‐embedded tissues with immunohistochemistry." (PMID 30160357, 2018). "The ectopic expression of miR-29a promotes angiogenesis and tumor cell proliferation through the down-regulation of anti-angiogenic genes such as Col4a2, Spry1 and Timp3." (PMID 28388561, 2017). "Many miR-21 targets code for tumor suppressors, with a role in inhibiting cell signaling, cell proliferation and migration, e.g. phosphatase and tensin homolog (PTEN) tumor suppressor, Sprouty1 (Spry1) and Sprouty2." (PMID 27513462, 2016).
tumor (continued). "We used an orthotopic xenograft model to analyze the role of Spry1 in TNBC tumor growth and metastasis in vivo." (PMID 26976794, 2016). "Tumor xenografts originating from Spry1 knockdown MDA-MB-231 cells grew slower, had increased E-cadherin expression, and yielded fewer lung metastases compared to control." (PMID 26976794, 2016). "In vivo, mice in which Spry1 is selectively deleted in T cells demonstrate enhanced responses to a tumor vaccine and subsequently reject tumors more robustly than Wt mice." (PMID 23166773, 2012). "Since, if SPRY1 silencing enhances tumor angiogenesis, then restoring SPRY1 expression should be an interesting way to reduce tumor growth." (PMID 20813052, 2010). "We further demonstrated in our xenograft tumor model that 16 K hPRL specifically enhanced the transcript-level of SPRY1 in the (murine) vascular compartment." (PMID 20813052, 2010). "Although we were unable to detect SPRY1 in the tumor samples of the in vivo experiment, the Ct values of SPRY1 in the HCT116 cells in vitro were very high but in detection rate." (PMID 20813052, 2010). "As the developing human tumors recruit mouse endothelial cells to form their vasculature in this model, it is possible to measure separately the levels of SPRY1 transcripts in the stromal-vascular and the tumor compartments." (PMID 20813052, 2010). "We further assessed the regulation of endothelial SPRY1 expression by 16 K hPRL in vivo in a mouse xenograft tumor model consisting of nude mice injected s.c." (PMID 20813052, 2010). "For example, SPRY1 was significantly upregulated in tumor-derived lymphatic endothelial cells." (PMID 34976204, 2022). "Indeed, suppression of Spry1 in rhabdomyosarcoma tumors with mutant Ras was sufficient to lead to complete tumor regression." (PMID 26976794, 2016). "It is known that solid tumor cells are in a relative hypoxic environment, and this less optimal growth condition may be associated with the major cytoplasmic cellular localization of Spry1 observed by tumor sample immunohistochemistry." (PMID 26976794, 2016). "Further evidence of their role as important tumour suppressors comes from a recent study of Spry1 null mice thyroids which demonstrated that Sprouty can act, independently of the ERK pathway, in hyperproliferative cells to induce senescence via NFκB signalling." (PMID 26075267, 2015). "Indeed, concomitant loss of Spry1 and Spry2 function results in tumorigenesis with significant PIN and invasive tumours only induced by codeletion of Spry1 and Spry2 in haploinsufficient phosphatase and tensin (Pten) mice." (PMID 26075267, 2015). "As such, our data identify Spry1 as a potentially novel target for enhancing tumor immunotherapy." (PMID 23166773, 2012). "Higher grade tumours had lower expression of Spry1 and Spry2." (PMID 21909357, 2011). "Based on these data, we hypothesized that SPRY1 might be an endogenous angiogenesis inhibitor and we therefore decided to study its properties in several angiogenesis models, including tumor-induced angiogenesis in mice." (PMID 20813052, 2010). "Moreover, SPRY2, a family member of SPRY1, has been shown to inhibit migration of tumor cells in response to serum and several growth factors." (PMID 20813052, 2010). "Here, after confirming upregulation of SPRY1 expression by 16 K hPRL both in vitro (in primary endothelial cells) and in vivo (in a mouse xenograft tumor model), we performed SPRY1-knockdown experiments to test the possible involvement of SPRY1 in regulating angiogenesis." (PMID 20813052, 2010). "Thus Macro-MMP9 and CD8+ Tex-SPRY1 form a positive feedforward cycle and anti-tumor ability." (PMID 39703499, 2024). "In addition, p38 activation along with an increase in basal ROS levels were found in Spry1KO clones compared to parental CM cell lines, suggesting that BRAFV600-mutant CM may restrain the activity of Spry1 to avoid oncogenic stress and to enable tumor growth." (PMID 32444628, 2020).
tumor (continued). "Although the precise molecular mechanism linking Spry1 to EMT needs further investigation, Spry1 expression appears to be critical for tumor induction, maintenance, and progression, and may potentially represent a novel vulnerability of CM harboring BRAF mutations." (PMID 32444628, 2020). "The identification of Spry1/2 as intracellular inhibitors that function to limit T-cell proliferation, survival, and memory formation, suggests that they may be attractive targets to improve tumor immunotherapy." (PMID 32731503, 2020). "Furthermore, inasmuch as tumor-induced T cell anergy inhibits the anti-tumor effector response, it is possible that blocking Spry1 during the effector phase of the anti-tumor response might further enhance the efficacy of tumor immunotherapy." (PMID 23166773, 2012). "Alternatively, Spry1 mediated negative regulation may hamper anti-tumor responses." (PMID 23166773, 2012). "Therefore, the re-expression of SPRY1 when tumor growth is abolished might be a powerful tool to monitor tumor response to angiostatic treatment or to decide on treatment strategies." (PMID 20813052, 2010). "Functionally, miR-21 promotes tumorigenesis by suppressing multiple tumor suppressor genes that usually restrain proliferation, invasion, and survival, including PTEN, PDCD4, and SPRY1." (PMID 41511367, 2026). "Together, there is evidence that SPRY1 and -2 are oncogenes in GB, whereas SPRY2 is a tumor suppressor in NB." (PMID 41516252, 2025). "Besides its ability to modulate MAPK signaling pathways, Spry1KO markedly induced cell cycle arrest and apoptosis, repressed cell proliferation in vitro, and impaired tumor growth in vivo, suggesting that Spry1 may display an oncogenic function in this tumor type." (PMID 39953610, 2025). "In this context, we have recently demonstrated that knockout of Spry1 (Spry1KO) in BRAFV600-mutant CM led to cell cycle arrest and apoptosis, repressed cell proliferation in vitro, and reduced tumor growth in vivo." (PMID 39953610, 2025). "Suppressing Spry1 reverses these phenotypes by impairment of EGFR signaling, and leads to a significant reduction in tumor growth in vivo." (PMID 26976794, 2016). "SPRY1 mRNA and protein levels are increased in lung cancer tissue while SPRY2 and 4 levels are decreased and they function as tumor suppressors in these tumor." (PMID 26392417, 2015). "Spry1 was found essential for ERMS cell proliferation and survival in vitro and ERMS tumor formation and maintenance in vivo." (PMID 24744103, 2014). "We noted that T cells with high reactivity toward RCAN1-4 presented significantly greater expression of many tumor-reactive T cell-related genes, most notably CCL20, SDC4, and SPRY1, with greater than twofold greater expression than T cells with low/no response to RCAN1-4." (PMID 41436600, 2026). "In NB, SPRY2 acts as a tumor suppressor, whereas the effects of SPRY1, -3, and -4 in NB have not been investigated so far, although the survival analysis revealed increased survival of NB patients with low SPRY3 levels in different datasets." (PMID 41516252, 2025). "Despite these findings, however, the impact of Spry1 on the tumor microenvironment (TME) and angiogenesis in CM has not been explored yet." (PMID 39953610, 2025). "miR-21-knock out reduced tumour development in vivo by negatively regulating the expression of Spry1, Pten, and Pdcd4, but miR-21-null mice did not have any other phenotypic anomalies." (PMID 39456841, 2024). "Therefore, we further segregated ECs into tumor ECs (TECs) and normal ECs (NECs) using the TEC marker genes ENG, INSR, PECAM1, and SPRY1." (PMID 38182557, 2024). "We describe changes in biological pathways across the normal to tumor spectrum and show that fibroblast growth factor (FGF) ligands are overexpressed in NPC tumors, while negative regulators of FGF signaling, including SPRY1, SPRY2, and LGALS3, are down-regulated early in carcinogenesis." (PMID 35394843, 2022).
tumor (continued). "SPRY1 and SPRY2 were among the most highly down-regulated genes in normal-adjacent regions when compared with normal controls and remained down-regulated in dysplasia and tumor." (PMID 35394843, 2022). "In contrast, SPRY1 expression was downregulated in LE, IT, CT, PNZ, and PAN tumor areas." (PMID 35910677, 2022). "Additionally, miR-21 can enhance tumor metastasis and angiogenesis by inhibiting anti-angiogenic genes such as TIMP3, COl4a2, and Spry1 in tumor-infiltrating myeloid cells." (PMID 34778378, 2021). "Here, we report that Spry1 knockdown (Spry1KO) in three BRAFV600-mutant CM cell lines markedly induced cell cycle arrest and apoptosis, repressed cell proliferation in vitro, and impaired tumor growth in vivo." (PMID 32444628, 2020). "Among these four genes, we determined that SOX7-activated SPRY1 and SLIT2, and SOX7-repressed TRIB3 and MTHFD2 could all differentially contribute to SOX7-mediated tumor suppression." (PMID 29757932, 2018). "Furthermore, they indicated that the Spry1 promoter is frequently methylated and that the Spry1 expression is accordingly decreased in human MTC samples, collectively suggesting that Spry1 is a candidate tumor-suppressor gene in MTC." (PMID 24744103, 2014). "Expression profiling by qRT-PCR with species-specific primers revealed that induction of SPRY1 expression by 16 K hPRL occurs only in the (murine) endothelial compartment and not in the (human) tumor compartment." (PMID 20813052, 2010). "Together, our results show that unlike in some tumors, where Spry may mediate tumor suppression, Spry1 plays a selective role in at least a subset of TNBC to promote the malignant phenotype via enhancing EGF-mediated mesenchymal phenotype." (PMID 26976794, 2016). "No SPRY1 expression could be detected in the human tumor compartment even after 40 cycles of PCR amplification." (PMID 20813052, 2010). "The top negative DEGs, including ABCB1, SPRY1, EREG, PIK3R1, SPTBN1, VIM, KDR, and others, exhibit a negative correlation with tumor purity while demonstrating a strong positive correlation with T‐cell infiltration, especially CD8+ T cells." (PMID 40567015, 2025). "Our study discerned that miR‐21‐related genes, such as ABCB1, SPRY1, ERGE, PIK3R1, SPTBN1, VIM, and others, which experienced downregulation in tumor sites, exhibited a negative correlation with tumor purity and a positive association with T cell infiltration, notably CD8+ T cells." (PMID 40567015, 2025). "Lambrechts and co-workers classified tumor endothelial cells in different clusters based on the marker genes identified; Lymphatic endothelial cells (PDPN+, PROX1+), tumor-derived blood endothelial cells (FLT1+, IGFBP3+, and SPRY1+), malignant, and non-malignant endothelial cells." (PMID 33763348, 2021).